SAMHD1 (SAM and HD domain containing deoxynucleoside triphosphate triphosphohydrolase 1)
Diseases named in the same sentence as SAMHD1 in open-access papers (continued):
Sharing a sentence is not in itself a finding about the gene and the disease.
tumor (continued). "As SAMHD1 function might influence cell proliferation, we first investigated whether SAMHD1 expression was associated with tumor differentiation grade or histologic type as a surrogate measure of tumor cell proliferation." (PMID 35158911, 2022). "SAMHD1 was proposed to rather act as a “mini driver”, meaning that mutations in SAMHD1 might only slightly increase evolutionary fitness of tumor cells." (PMID 34480199, 2022). "Therefore, we conclude that the disturbance of the dNTP pool caused by SAMHD1 mutations in T-PLL leads to a benefit for the tumor cells, since increased intracellular dNTPs promote cell cycle progression, proliferation, and survival of the cells." (PMID 29352181, 2018). "Inactivating mutations in SAMHD1, which lead to increased dNTP levels, promote tumor cell survival." (PMID 29352181, 2018). "Moreover, it has been proposed that SAMHD1 might fulfill the requirements of a driver gene in tumor development or might promote a so-called mutator phenotype." (PMID 34480199, 2022). "Therefore, loss of SAMHD1 in tumor cells could have several consequences, including loss of checkpoint response, increase in cytoplasmic NAS derived from TEs, and increase in ssDNA fragments in the cytosol, released from stalled replication forks." (PMID 35602594, 2022). "From our in‐house HCC samples, we found that higher nuclear SAMHD1 protein levels were correlated with less advanced tumor stages, longer disease‐free survival (DFS), and favorable overall survival (P = 0.055)." (PMID 39679869, 2025). "In this study, we observed higher nuclear SAMHD1 levels in tumor tissues from clinical HCC samples compared to paratumor tissues." (PMID 39679869, 2025). "We found HSP90 expression had variable influences on SAMHD1 expression and tumor patient’s survival." (PMID 41392286, 2025). "The approach of selectively depleting SAMHD1 in tumor cells, as described in this study, holds promising potential for future therapeutic applications." (PMID 41392286, 2025). "Hepatocyte‐specific SAMHD1 knockout mice, generated by crossing SAMHD1fl/fl mice with Alb‐cre mice, showed accelerated tumor progression in a diethylnitrosamine (DEN)‐induced HCC model." (PMID 39679869, 2025). "To investigate factors contributing to increased nuclear levels of SAMHD1 in tumor cells, we simulated the hypoxic microenvironment in proliferating HCC cells using glucose and oxygen deprivation (OGD)." (PMID 39679869, 2025). "Collectively, these results suggest that increased nuclear SAMHD1 levels in tumor tissue of HCC are correlated with positive clinical outcomes." (PMID 39679869, 2025). "SAMHD1 is a deoxynucleoside triphosphate (dNTP) triphosphohydrolase and can mitigate the anti-tumor effect of DAC by converting 5-aza-dCTP to its inactive form 5-aza-dC." (PMID 39930152, 2025). "In summary, SAMHD1 reduction following STA-9090 treatment was substantiated across 23 distinct tumor cell lines derived from nine diverse tissue types." (PMID 41392286, 2025). "In our study, we found that HSP90 inhibitors induced SAMHD1 depletion, leading to the activation of innate immune responses and triggering apoptosis in tumor cells." (PMID 41392286, 2025). "Our strategy for targeting SAMHD1 differs from general SAMHD1 inhibition in that it selectively targets tumor cells." (PMID 41392286, 2025). "Treatment with various HSP90 inhibitors, including the clinically approved drug Pimitespib, resulted in efficient SAMHD1 depletion in a variety of tumor cell types." (PMID 41392286, 2025). "In this study, we developed a strategy to selectively target and deplete tumor-specific SAMHD1 while minimizing its impact on normal cells." (PMID 41392286, 2025). "In this study, we introduced a novel approach to selectively and efficiently deplete SAMHD1 in various tumor cells while preserving its expression in normal cells." (PMID 41392286, 2025).
tumor (continued). "IHC and IF results of SAMHD1 staining indicated a predominant nuclear localization of SAMHD1 in HCC mouse tumor tissues, whereas in control mouse liver tissues, SAMHD1 was primarily cytoplasmic." (PMID 39679869, 2025). "Hepatocyte‐specific knockout of SAMHD1 exacerbates the progression of tumor growth in a DEN‐induced HCC mouse model." (PMID 39679869, 2025). "As SAMHD1 displayed increased nuclear staining in HCC tumor tissues, we aimed to identify potential nuclear‐interacting partners of SAMHD1." (PMID 39679869, 2025). "Elevated nuclear SAMHD1 levels in tumors correlate with favorable prognosis, and hepatocyte‐specific SAMHD1 knockout in mice accelerates tumor growth." (PMID 39679869, 2025). "Conversely, hepatocyte‐specific SAMHD1 knockout mice displayed accelerated tumor growth and migration." (PMID 39679869, 2025). "Since its discovery, several broad regulatory functions have been attributed to SAMHD1 dNTPase activity including restriction of viral replication, maintenance of genome stability, cell cycle progression, tumor suppression, and immune responses." (PMID 40552831, 2025). "Our study found that hepatocyte‐specific SAMHD1 knockout did not affect tumorigenesis rates in the DEN‐induced HCC model, suggesting SAMHD1 plays a limited role in tumor initiation." (PMID 39679869, 2025). "SAMHD1 staining was more prominent in the nuclei of tumor tissues, whereas in paratumor tissues, it was primarily localized in the cytoplasm." (PMID 39679869, 2025). "SAMHD1 also plays a role in tumor development and progression by modulating the cell cycle and DNA damage repair mechanisms." (PMID 39655951, 2025). "Expression of SAMHD1 was evaluated by immunohistochemistry in available retrospectively collected post-NACT tumor biopsies and samples were stratified according to SAMHD1 expression." (PMID 37667113, 2024). "The overexpression of SAMHD1 in RCC tumor tissues was also related to worse survival prognoses in groups with high SAMHD1 expression, especially for patients with the ccRCC subtype." (PMID 37009792, 2023). "To further investigate the role of SAMHD1 in vivo, we examined the tumor growth in a xenograft mouse model established by Ctrl and SAMHD1-KD LY1 cells." (PMID 37781035, 2023). "We next investigated the effect of SAMHD1 on the apoptosis of tumor cells induced by genotoxic insults." (PMID 37081042, 2023). "Immunohistochemistry and western blot analysis showed higher protein expression levels of SAMHD1 in tumor tissues than in the paired normal tissues." (PMID 37009792, 2023). "In this study, we reported that sterile alpha motif and HD domain-containing protein 1 (SAMHD1) deficiency induced STING expression and inhibited tumor growth in DLBCL." (PMID 37781035, 2023). "The phosphorylation level of cortactin was positively correlated with the expression of SAMHD1 in tumor tissues." (PMID 37009792, 2023). "In our study, we found that a subset of DLBCL patients with SAMHD1-positive expression was associated with poor prognosis, consistent with the promoting effects of SAMHD1 on tumor growth." (PMID 37781035, 2023). "SAMHD1 mRNA levels were higher in tumor tissues than in adjacent normal tissues from patients with the ccRCC subtype." (PMID 37009792, 2023). "GBM samples express a significantly higher level of SAMHD1 compared to non-tumor brain samples in both datasets." (PMID 36139652, 2022). "Cases with blastoid/pleomorphic morphology had higher SAMHD1 expression (P = 0.028) and SAMHD1 was also correlated to tumor cell proliferation (P = 0.016)." (PMID 34738194, 2022). "SAMHD1 silencing cooperated with radiotherapy to inhibit tumor growth and increase CD86+MHC-IIhigh M1 proportion and CD8+ T cell infiltration in vivo." (PMID 36578072, 2022). "In the tumor microenvironment, both SAMHD1 silencing and radiotherapy increased the ratio of CD8+ T cells in the tumor tissues, while the combined therapy had more obvious effects." (PMID 36578072, 2022).
tumor (continued). "In the mouse GBM xenograft model, Vpx-mediated SAMHD1 depletion reduced tumor growth and SAMHD1 knockout (KO) improved survival." (PMID 36139652, 2022). "In line with tumor data, significant heterogeneity in SAMHD1 expression has also been reported in normal human tissues, being ubiquitously expressed in lymphoid cells." (PMID 35158911, 2022). "To assess the effect of Vpx-mediated SAMHD1 depletion on GBM tumor progression, we established LN-229 cell xenografts on the left and right flanks of athymic nude mice." (PMID 36139652, 2022). "The combined effects of SAMHD1 silencing and radiation on tumor cell growth and STING pathway activation were also evaluated with colony formation and CCK8 assay." (PMID 36578072, 2022). "Here, we report that tumor samples from GBM patients express a high level of SAMHD1, emphasizing SAMHD1’s importance." (PMID 36139652, 2022). "Here, we designed experiments in vitro and in vivo to investigate and verify the function of SAMHD1 in anti-tumor immunity and radiotherapy." (PMID 36578072, 2022). "SAMHD1 is a multifaceted enzyme with various functions including tumor suppression through DNA repair activity and maintenance of steady-state intracellular dNTP levels, which has been involved in HIV-1 replication." (PMID 35023831, 2022). "Here, we found that SAMHD1 expression was significantly associated with poorer prognostic clinical outcomes, including DFS and OSCD in all tumor types analyzed, including advanced disease cases of breast, ovarian, and NSCLC cancer." (PMID 35158911, 2022). "In a subsequent study, SAMHD1 mRNA expression in tumor and adjacent healthy tissue was assessed in a larger cohort of 238 non-small lung cancer (NSLC) patients: Again, expression of SAMHD1 mRNA was significantly reduced in tumor compared to healthy specimens." (PMID 34480199, 2022). "Expression of SAMHD1 across different tumor types was evaluated by immunohistochemistry and samples were stratified according to SAMHD1 expression." (PMID 35158911, 2022). "The diagnosis of MCL was confirmed by the expression of CD20, CD5, cyclin D1, SOX11, and SAMHD1 of tumor cells." (PMID 34976810, 2021). "We found that R-loops are highly enriched at transcription-replication conflict regions of the genome in fibroblast of patients bearing SAMHD1 mutation, which is the AGS-associated-gene mutation most frequently reported with tumor and malignancies." (PMID 33857133, 2021). "The full-length SAMHD1 acts as an anti-tumor factor by increasing the cell sensitivity to chemotherapy drugs." (PMID 30717368, 2019). "Incorporation of exon-4 of SAMHD1 has been linked to a higher prevalence of HBV- and HCV-related HCC, which leads to an abnormal SAMHD1 translation termination that weakens the anti-tumor activity of SAMHD1." (PMID 30717368, 2019). "Through this finely-tuned activity, SAMHD1 modulates anti-proliferative and tumor-suppressive functions, and the life cycle of several DNA and retroviruses." (PMID 31600877, 2019). "Using the same protocol we evaluated SAMHD1 dephosphorylation during mitotic exit in the tumor cell line U2OS and confirmed that the pattern of dephosphorylation of SAMHD1 paralleled that of pThr-CDK substrates." (PMID 30039733, 2018). "Remarkably, the timing of SAMHD1 phosphorylation is the same in normal and tumor cells, suggesting a general regulatory mechanism, independent of cell transformation." (PMID 30039733, 2018). "SAMHD1 expression levels in tumor and surrounding non-tumor tissues collected from 7 hepatocarcinoma patients were analyzed by western blot." (PMID 28978134, 2017). "Notably, nuclear SAMHD1 decreases at more advanced tumor stages, and higher nuclear SAMHD1 correlates with favorable prognostic outcomes." (PMID 39679869, 2025).
tumor (continued). "Another potential strategy involves the development of small molecule inhibitors of SAMHD1, although these inhibitors face difficulties in selectively targeting SAMHD1 in tumor cells while sparing normal cells, which remain critical for immune function and viral defense." (PMID 41392286, 2025). "Moreover, nuclear SAMHD1 levels decline in advanced tumor stages, with higher SAMHD1 nuclear staining correlating with favorable prognostic outcomes." (PMID 39679869, 2025). "Collectively, these findings suggest that nuclear SAMHD1 plays an anti‐tumor role in HCC." (PMID 39679869, 2025). "STA-9090 was the most effective drug for depleting SAMHD1 in the tumor cell line THP-1." (PMID 41392286, 2025). "As we observed that nuclear SAMHD1 expression increased in tumor tissue compared to adjacent non‐cancerous tissues, it was intuitively expected that nuclear SAMHD1 may play a pro‐tumor role." (PMID 39679869, 2025). "Furthermore, hepatocyte‐specific SAMHD1 knockout accelerates tumor development in DEN‐induced HCC mouse models." (PMID 39679869, 2025). "Although the nuclear‐over‐cytoplasmic ratio of SAMHD1 was notably elevated in tumor tissues compared to adjacent non‐tumor tissues, we sought to investigate whether the overall SAMHD1 protein and mRNA levels are altered in tumor tissue." (PMID 39679869, 2025). "Notably, SAMHD1 nuclear staining intensity decreased as the tumor stage advanced, while higher SAMHD1 nuclear staining correlated with better survival outcomes, indicating its potential as a favorable prognostic marker." (PMID 39679869, 2025). "In addition, the levels of nuclear SAMHD1 staining decreased in tumor tissues from patients with more advanced stages of HCC." (PMID 39679869, 2025). "We demonstrated that SAMHD1 protein levels in tumor cells are regulated by HSP90 complexes." (PMID 41392286, 2025). "Although their downregulation was confirmed in additional in vitro experiments, only TCP1 could be confirmed in patients, i.e. TCP1-low-expressing tumors showed also low-levels of SAMHD1 expression by qRT-PCR on tumor biopsies." (PMID 37667113, 2024). "Heterotypic 3D cultures including tumor and immune cells were used to investigate the molecular mechanisms responsible of SAMHD1 depletion through whole transcriptomic profiling, immune infiltration capacity and subsequent delineation of dysregulated immune signaling pathways." (PMID 37667113, 2024). "Interestingly, only ccRCC had significantly upregulated mean SAMHD1 mRNA expression in tumor tissues compared with normal tissues." (PMID 37009792, 2023). "Indeed, SAMHD1 knockdown significantly increases chemosensitivity to cisplatin and doxorubicin in tumor cells." (PMID 37081042, 2023). "This has led us to explore the effect of SAMHD1 on tumor cell survival under genotoxic insults." (PMID 37081042, 2023). "Moreover, USP7 inhibitor sensitizes tumor cells to chemotherapeutic agents by decreasing SAMHD1 in vitro and in vivo." (PMID 37081042, 2023). "SAMHD1 silencing significantly suppressed tumor growth in vivo." (PMID 36578072, 2022). "SAMHD1 is also considered to have tumor suppressor activity." (PMID 34738194, 2022). "The source of the endogenous nucleic acids is as yet unclear; however, the various functions of SAMHD1, when inactive, could promote their accumulation and possibly lead to tumor-promoting inflammation." (PMID 34480199, 2022). "SAMHD1 might influence a variety of hallmarks, potentially including tumor-promoting inflammation as an enabling characteristic in neoplastic disease." (PMID 34480199, 2022). "One of the potential opportunities in oncology is to find targets that small molecules can target to achieve an effect on the tumor, as this may be the case of SAMHD1." (PMID 35158911, 2022). "This also suggests that not only the enzymatic activity of SAMHD1 might be responsible for tumor development." (PMID 34480199, 2022).
tumor (continued). "Radiotherapy or SAMHD1 silencing could inhibit tumor growth alone, but the combination of them would slow tumor growth more significantly." (PMID 36578072, 2022). "Moreover, the diverse functions of SAMHD1 make it difficult to pinpoint the exact mechanisms how SAMHD1 contributes to tumor development." (PMID 34480199, 2022). "To investigate whether increasing CDA levels in vivo sensitizes SAMHD1-deficient cells to PNPi, we established CEM-YFP control and CEM-CDA bilateral subcutaneous tumors in NCG mice and initiated PNPi treatment once tumor volumes reached 100 mm3." (PMID 35653193, 2022). "There is one therapeutic implication of our findings that SAMHD1 inhibition and radiotherapy may be a rational combination to inhibit tumor growth and enhance anti-tumor immunity." (PMID 36578072, 2022). "PNP inactivation is synthetically lethal with SAMHD1 deficiency; thus, PNPi may be particularly effective for the treatment of patients stratified by tumor cell SAMHD1 expression." (PMID 35653193, 2022). "We also examined the synergistic anti-tumor effects of SAMHD1 silencing and radiation." (PMID 36578072, 2022). "We hypothesized that SAMHD1 silencing and radiotherapy cooperated to inhibit tumor growth via altering tumor microenvironment." (PMID 36578072, 2022). "In addition, SAMHD1 knockdown combined with radiotherapy inhibited tumor growth and induced anti-tumor immunity via promoting macrophage M1 polarization and CD8+ T cell infiltration." (PMID 36578072, 2022). "Moreover, SAMHD1 downregulation and radiation cooperated to inhibit tumor growth and enhance anti-tumor immune responses through macrophage M1 polarization and CD8+ T cell infiltration." (PMID 36578072, 2022). "However, SAMHD1 acts also as a tumor suppressor through its activity as a dNTP triphosphohydrolase to diminish intracellular dNTP pool and inhibit DNA replication." (PMID 30862120, 2019). "In conclusion, we identified novel recurrently mutated genes in T-PLL, including PTPRC, regulating the JAK/STAT pathway, epigenetic regulators like PRDM2 and HERC1/2, and genes involved in DNA damage response and DNA repair like SAMHD1, which has most likely a tumor-suppressor function in T-PLL." (PMID 29352181, 2018). "Dose adjustments and addition of potential strategies to inhibit SAMHD1 at the wrong time might jeopardize possible therapeutic improvements or lead to worse outcomes due to excess toxicity or inhibition of SAMHD1 tumor suppressor functions." (PMID 30341277, 2018). "In Summary, SAMHD1 acetylation promotes tumor growth by facilitating G1/S cell cycle progression." (PMID 28978134, 2017). "Since dNTP metabolism and balance is critical in carcinogenesis, the dNTPase activity of SAMHD1 may mediate its tumor suppressive function." (PMID 26416562, 2015). "Together these findings support the hypothesis that SAMHD1, through its dNTPase function, could potentially act as a tumor suppressor." (PMID 26416562, 2015). "In the case of SAMHD1, recent work has highlighted that SAMHD1 may qualify as a tumor suppressor gene, and thus play roles in DNA damage response, through its ability to regulate the dNTP pool, the levels of these being important for genome stability." (PMID 24795708, 2014). "Moreover, nuclear SAMHD1 suppresses tumor cell mitosis, providing an expansion advantage to cells with lower nuclear SAMHD1 levels, which may contribute to the observed shift with tumor progression." (PMID 39679869, 2025). "Thus, as interleukins and their signaling pathways identified above, are potent chemoattractant for immune cells and may determine tumor immune infiltration, we evaluated the capacity of immune cells to infiltrate in SAMHD1 KO and WT T47D spheroids." (PMID 37667113, 2024).